NEURL1 (neuralized E3 ubiquitin protein ligase 1)
Description:
Plays a role in hippocampal-dependent synaptic plasticity, learning and memory. Involved in the formation of spines and functional synaptic contacts by modulating the translational activity of the cytoplasmic polyadenylation element-binding protein CPEB3. Promotes ubiquitination of CPEB3, and hence induces CPEB3-dependent mRNA translation activation of glutamate receptor GRIA1 and GRIA2. Can function as an E3 ubiquitin-protein ligase to activate monoubiquitination of JAG1 (in vitro), thereby regulating the Notch pathway. Acts as a tumor suppressor; inhibits malignant cell transformation of medulloblastoma (MB) cells by inhibiting the Notch signaling pathway.
Synonyms: h-neu; NEURL; RNF67; neu-1; NEUR1; bA416N2.1; neu
Tractability: Antibody: its Gene Ontology location is reachable by antibodies, with high confidence; UniProt places it where antibodies can reach, with medium confidence. PROTAC: ubiquitination databases record sites on it.
Gene: Protein-coding gene on chromosome 10 (103,493,705 to 103,592,546, forward strand). Ensembl gene ENSG00000107954.
Subcellular location: Cytoplasm, perinuclear region; Cell membrane; Perikaryon; Cell projection, dendrite; Postsynaptic density
Pathways (Reactome):
Disease: Constitutive Signaling by NOTCH1 HD Domain Mutants; Constitutive Signaling by NOTCH1 HD+PEST Domain Mutants; Constitutive Signaling by NOTCH1 PEST Domain Mutants
Signal Transduction: Activated NOTCH1 Transmits Signal to the Nucleus; NOTCH2 Activation and Transmission of Signal to the Nucleus; NOTCH3 Activation and Transmission of Signal to the Nucleus
Gene Ontology:
Molecular function: protein binding; translation regulator activity; ubiquitin protein ligase activity; ubiquitin-protein transferase activity
Biological process: negative regulation of cell population proliferation; negative regulation of Notch signaling pathway; positive regulation of apoptotic process; cellular response to amino acid stimulus; nervous system development; positive regulation of dendritic spine development; positive regulation of filopodium assembly; positive regulation of long-term neuronal synaptic plasticity; positive regulation of synapse maturation; protein monoubiquitination; regulation of Notch signaling pathway; protein ubiquitination; regulation of cell communication; regulation of postsynapse assembly; regulation of signaling; regulation of translation; skeletal muscle tissue development
Cellular component: plasma membrane; apical dendrite; dendritic spine; perikaryon; postsynaptic density; cytoplasm; dendrite; glutamatergic synapse; perinuclear region of cytoplasm
Genetic constraint (gnomAD): Loss-of-function variants: 26 observed, 34.84 expected, observed/expected ratio (o/e) 0.75, 90% interval 0.55 to 1.04. The synonymous counts are far from expectation, so gnomAD's model fits this gene poorly and the ratio says little. Missense variants: 761 observed, 727.77 expected, observed/expected ratio (o/e) 1.05, 90% interval 0.98 to 1.11. Synonymous variants: 400 observed, 332.92 expected, observed/expected ratio (o/e) 1.2, 90% interval 1.11 to 1.3.
Homologues: Orthologues: dog NEURL1 (97% identical), macaque NEURL1 (96% identical), pig NEURL1 (96% identical), rat Neurl1 (95% identical), mouse Neurl1a (94% identical), rabbit NEURL1 (93% identical), guinea pig NEURL1 (91% identical), chimpanzee NEURL1 (83% identical), tropical clawed frog neurl1 (74% identical), zebrafish neurl1aa (67% identical). Paralogues in human: NEURL1B (40% identical), NEURL4 (24% identical), NEURL3 (17% identical).
Diseases named in the same sentence as NEURL1 in open-access papers:
NEURL1 is named in the same sentence as 24 diseases in open-access papers, as found by Europe PMC text mining. Sharing a sentence is not in itself a finding about the gene and the disease. The quoted sentences say what the papers report.
astrocytomas (2 papers, 2014 to 2016). "The chromosomal fragment 10q25.1 encoding Neurl1 has been found to be frequently lost in grade II astrocytomas and GBM." (PMID 25601901, 2014). "Moreover, expression of human Neurl1 was nearly absent in high-grade astrocytoma and the majority of investigated glioma cell lines in contrast to the normal brain tissue." (PMID 25601901, 2014).
medulloblastoma (2 papers, 2010 to 2022). A malignant, invasive embryonal neoplasm arising from the cerebellum. "NEURL1 is a highly conserved E3 ubiquitin ligase which was reported to be a tumor suppressor in medulloblastoma through its regulation of Jagged1 levels to influence the Notch signaling pathway." (PMID 35641855, 2022).
adenoma (1 paper, 2023). A neoplasm arising from the epithelium. "We collected the resected carcinoma tissues from CRC patients and conducted immunohistochemical (IHC) staining analysis to examine the expression of some representative genes including NEK8, CHRM3, ANO7, B3GNT6, NEURL1, ODC1 and KCNMA1 in colon normal tissue, adenoma tissue and carcinoma tissues." (PMID 36944972, 2023).
astrocytic tumor (1 paper, 2019). A glial tumor of the brain or spinal cord showing astrocytic differentiation. "NEURL1 is an important determinant of neural tissue differentiation and functions as a tumor suppressor which is inactivated during malignant progression of astrocytic tumors." (PMID 30785874, 2019).
breast carcinoma (1 paper, 2021). "Our results show that NEURL1 was specifically upregulated, and the high expression predicted high RFS in LumB-subtype breast cancer (p < 0.05), which is consistent with the prognostic conclusion of all breast cancer." (PMID 33644115, 2021).
Cognitive impairment (1 paper, 2024). Abnormal cognition is characterized by deficits in thinking, reasoning, or remembering. "The identification of PDZD2 and NEURL1 genes, which have been linked to cognitive impairments related to learning and memory, serves as supportive evidence for the efficacy of the models employed." (PMID 38472245, 2024).
colon cancer (1 paper, 2023). "We discovered new colon cancer related genes including AC007952.4, NEK8, CHRM3, ANO7, B3GNT6, NEURL1, ODC1 and KCNMA1." (PMID 36944972, 2023).
diabetic foot ulcers (1 paper, 2024). "Since NEURL1 is a positive regulator of the Notch receptor and Notch signaling may be a therapeutic target in DFU healing, further research on the role of NEURL1 in diabetic foot ulcers and as a therapeutic target should be investigated." (PMID 39335453, 2024).
dystroglycanopathy (1 paper, 2024). "Further investigations may be warranted to determine whether NEURL1 mutations could lead to dystroglycanopathy phenotypes." (PMID 38296890, 2024).
leiomyoma (1 paper, 2022). A well-circumscribed benign smooth muscle neoplasm characterized by the presence of spindle cells with cigar-shaped nuclei, interlacing fascicles, and a whorled pattern. "Our study indicated increased expression levels of RP11-225H22 and its overlapped transcript NEURL1 in leiomyomas which may contribute to the reduced levels of Jagged1 reported in leiomyomas." (PMID 35641855, 2022).
mastitis (1 paper, 2023). Inflammation of breast tissue during lactation or postpartum due to an obstructed duct or infection. "The neutralized E3 ubiquitin protein ligase 1 (NEURL1) gene on BTA26 has a known SNP that is located in intron 1 and has been linked to mastitis risk in cattle." (PMID 36669036, 2023).
muscular dystrophy (1 paper, 2024). Muscular dystrophy (MD) refers to a group of more than 30 genetic diseases characterized by progressive weakness and degeneration of the skeletal muscles that control movement. "Furthermore, a unique variant in JAG1, which is not directly related to skeletal muscle disease, has been found to possess a modifying effect on muscular dystrophy, and NEURL1 had been found to affect the signaling activity of JAG1 by directly enhancing its ubiquitination." (PMID 38296890, 2024).
soft tissue sarcoma (1 paper, 2019). A malignant neoplasm arising from muscle tissue, adipose tissue, blood vessels, fibrous tissue, or other supportive tissues excluding the bones. "Using a random forest analysis, novel diagnostic markers were identified that may distinguish between soft tissue sarcoma subtypes within these three groups, including NEURL1 that was highly expressed in SS as compared to MPNST." (PMID 30785874, 2019).
sterility (1 paper, 2016). "In mice, NOTCH1 gain-of-function resulted in reduced male fertility due to failure of spermatogenesis, while immotile spermatozoa and sterility was detected in NEURL1 null mice." (PMID 27079378, 2016).
synovial sarcoma (1 paper, 2019). "For group 2 (MPNST and SS) genes related to neural differentiation such as NEURL1 and NPAS1 were identified, which were found to be upregulated in synovial sarcomas, while SCD, an enzyme involved in fatty acid biosynthesis, is more highly expressed in MPNST." (PMID 30785874, 2019).
tumor (10 papers, 2019 to 2025). "Neurl1 overexpression is known to downregulate Notch signaling, which is a key pathway associated with tumor growth, metastases and chemoresistance." (PMID 34359773, 2021). "Neuralized-like protein 1 (NEURL1) is a conserved E3 ligase investigated as a candidate tumor suppressor." (PMID 35847032, 2022). "According to studies, NEURL1 is significantly down-regulated in medulloblastoma cells through histone modification and exhibits various tumor suppressor properties, including promotion of cell apoptosis and suppression of tumor growth, angiogenesis, and invasion." (PMID 35847032, 2022).
NEURL1 also shares sentences with these, for which no sentence is quoted: atrial fibrillation (3 papers); cancer (3); neuroblastoma (2); clear cell renal cell cancer (1); hearing loss (1); migraine (1); Oesophageal adenocarcinoma (1); pancreatic cancer (1).